NRGN (neurogranin)
Description:
Acts as a 'third messenger' substrate of protein kinase C-mediated molecular cascades during synaptic development and remodeling. Binds to calmodulin in the absence of calcium (By similarity).
Synonyms: RC3; hng
Tractability: PROTAC: its protein half-life has been measured.
Gene: Protein-coding gene on chromosome 11 (124,739,939 to 124,747,210, forward strand). Ensembl gene ENSG00000154146.
Pathways (Reactome):
Neuronal System: Long-term potentiation
Gene Ontology:
Molecular function: calmodulin binding; phosphatidic acid binding; phosphatidylinositol-3,4,5-trisphosphate binding
Biological process: nervous system development; signal transduction; associative learning; positive regulation of long-term synaptic potentiation; postsynaptic modulation of chemical synaptic transmission; telencephalon development
Cellular component: cytosol; axon; dendrite; dendritic spine head; glutamatergic synapse; mitochondrial membrane; neuronal cell body; postsynapse; postsynaptic membrane; trans-Golgi network transport vesicle membrane
Genetic constraint (gnomAD): Loss-of-function variants: 0 observed, 1.54 expected, observed/expected ratio (o/e) 0, 90% interval 0 to 1.54. That is too few expected variants to judge how well the gene tolerates losing a copy. Missense variants: 82 observed, 88.73 expected, observed/expected ratio (o/e) 0.92, 90% interval 0.77 to 1.11. Synonymous variants: 46 observed, 41.45 expected, observed/expected ratio (o/e) 1.11, 90% interval 0.88 to 1.42.
Homologues: Orthologues: chimpanzee NRGN (100% identical), macaque NRGN (100% identical), guinea pig NRGN (97% identical), mouse Nrgn (96% identical), pig NRGN (96% identical), rabbit NRGN (96% identical), rat Nrgn (96% identical), dog NRGN (95% identical), zebrafish spa17 (47% identical), zebrafish nrgna (45% identical), tropical clawed frog spa17 (44% identical).
Diseases named in the same sentence as NRGN in open-access papers:
NRGN is named in the same sentence as 73 diseases in open-access papers, as found by Europe PMC text mining. Sharing a sentence is not in itself a finding about the gene and the disease. The quoted sentences say what the papers report.
Alzheimer disease (56 papers, 2015 to 2026). A progressive, neurodegenerative disease characterized by loss of function and death of nerve cells in several areas of the brain leading to loss of cognitive function such as memory and language. "Conversely, DDX5 downregulates NRGN, a gene crucial for synaptic plasticity and often associated with neurological and mental disorders, particularly Alzheimer’s disease, where it serves as a reliable biomarker for synaptic dysfunction." (PMID 41333436, 2025). "The association of novel biomarkers such as CSF MCP-1 and neurogranin with core biomarkers such as t-tau and p-tau has improved their diagnostic accuracy for discriminating between Alzheimer’s disease and dementia with Lewy bodies." (PMID 33578866, 2021). "CSF MCP-1 and neurogranin are elevated in the early and late stages of Alzheimer’s disease and are associated with an enhanced rate of cognitive decline and neurodegeneration." (PMID 33578866, 2021). "An example CH-DMR is shown within the gene body of NRGN, which encodes the brain-specific protein neurogranin, recently identified as a cerebral spinal fluid biomarker for Alzheimer’s disease." (PMID 33888138, 2021). "Most studies have investigated NRGN genetic polymorphisms in adults with schizophrenia and in cerebrospinal fluid (CSF) in Alzheimer’s disease, relating NRGN to learning and memory impairment." (PMID 33915030, 2021). "YKL-40 and neurogranin are promising additional cerebrospinal fluid (CSF) biomarkers for Alzheimer’s disease (AD) which reflect different underlying disease mechanisms." (PMID 32568193, 2020). "Neurogranin levels are markedly reduced in the frontal cortex and hippocampus in Alzheimer’s disease, indicating loss of post-synaptic elements." (PMID 30649659, 2019). "Several studies illustrate the potential of neurogranin as biomarker for Alzheimer’s disease (AD), the most common cause of dementia." (PMID 28854881, 2017). "Furthermore, neurodegeneration-associated markers, such as Alzheimer’s disease (AD)-related molecules and neurogranin hold prognostic significance, particularly in cognitive outcomes for people with MCI and PD." (PMID 40991070, 2025). "Neurogranin in CSF has been suggested as a biomarker of early synaptic loss and degeneration in Alzheimer’s disease and may be a useful predictor of disease progression." (PMID 33578866, 2021). "We provide evidence for how previously identified GWAS loci for schizophrenia (NRGN), Parkinson’s disease, and Alzheimer’s disease (PARK16 and MAPT loci) could increase the risk for disease at a molecular level." (PMID 27287230, 2016). "The relevance of neurogranin in mTBI also resonates with findings from Alzheimer’s disease and related disorders." (PMID 40981206, 2025). "In subgroups of patients, CSF levels of presynaptic neurexin 3 (NRXN3), postsynaptic neurogranin (NRGN) and Alzheimer’s disease biomarkers were measured for comparison." (PMID 40840974, 2025). "While neurogranin has been extensively studied as a cerebrospinal fluid (CSF) biomarker in Alzheimer’s disease and other neurodegenerative conditions, its utility in the context of mTBI is a relatively nascent field." (PMID 40981206, 2025). "LC-MS/MS has already been successfully applied in Alzheimer’s disease and related neurodegenerative disorders to quantify neurogranin in cerebrospinal fluid and plasma." (PMID 40981206, 2025). "In humans, neurodegenerative diseases such as Alzheimer’s disease lead to a depletion of NRGN expression in the brain and an elevation of NRGN levels in the cerebrospinal fluid, changes that are associated with diminished cognitive performance." (PMID 38732149, 2024). "NRGN is involved in synaptic plasticity, and increased levels have been observed in the cerebrospinal fluid of Alzheimer’s disease patients." (PMID 39590217, 2024). "One study investigating the relationship between neurogranin and Alzheimer’s disease utilized data from the Alzheimer’s Disease Neuroimaging Initiative (ADNI) database." (PMID 38920976, 2024).
Alzheimer disease (continued). "With regards to neurogranin, the levels of this protein were analyzed in only one human post-mortem sample of patients with Alzheimer’s disease and DLB." (PMID 36139038, 2022). "Cerebrospinal fluid (CSF) β-site amyloid precursor protein cleaving enzyme 1 (BACE1), neurogranin and the neurogranin/BACE1 ratio are proposed markers for Alzheimer’s disease." (PMID 36262371, 2022). "A recent meta-analysis demonstrated that CSF neurogranin levels were significantly greater in Alzheimer’s disease patients compared with individuals with normal cognitive function." (PMID 33578866, 2021). "Elevated levels of CSF neurogranin at the mild cognitive impairment stage predicted progression to Alzheimer’s disease dementia (HR: 12.8, 95% CI: 1.6–103.0)." (PMID 33578866, 2021). "Studies have shown elevated levels of CSF neurogranin in patients with mild cognitive impairments and in the predementia stage of Alzheimer’s disease." (PMID 33578866, 2021). "Neurogranin (Ng) is a 78 amino acid neuronal protein and a biomarker candidate for Alzheimer's disease (AD)." (PMID 33249594, 2021). "Overall, the data show that CSF neurogranin levels are elevated at the initial clinical stage of Alzheimer’s disease and are specific to the disease." (PMID 33578866, 2021). "In another study, CSF neurogranin levels were significantly higher in patients with prodromal Alzheimer’s disease compared to individuals with mild cognitive impairment." (PMID 33578866, 2021). "A number of studies have shown that CSF neurogranin levels can predict the progression of Alzheimer’s disease." (PMID 33578866, 2021). "In the last few decades, research has focused on the possible role of neurogranin as a biomarker for synaptic dysfunction in neurodegenerative diseases, such as Alzheimer’s disease (AD)." (PMID 34943576, 2021). "C‐terminal fragments, along with full‐length forms of neurogranin (Ng) have been previously found at higher concentration in CSF from Alzheimer ́s disease patients." (PMID 33249594, 2021). "In the ADNI cohort study, CSF neurogranin levels were significantly increased in Alzheimer’s disease patients with dementia and patients with stable mild cognitive impairment and progressive cognitive impairment compared with controls." (PMID 33578866, 2021). "In a cross-sectional multicenter study, CSF neurogranin levels were significantly greater in Alzheimer’s disease patients compared with subjects with frontotemporal dementia and healthy controls with normal cognitive function." (PMID 33578866, 2021). "Accumulating data suggest cerebrospinal fluid (CSF) neurogranin (Ng) as a potential biomarker for cognitive decline and neurodegeneration in Alzheimer disease (AD)." (PMID 32421689, 2020). "Alzheimer’s disease affects the brain regions where neurogranin is mainly expressed, i.e., the hippocampus, amygdala, and the neocortex." (PMID 30649659, 2019). "Several studies have shown that CSF neurogranin concentrations are elevated in patients with mild cognitive impairment due to Alzheimer’s disease as well as in patients with Alzheimer’s disease [10•, 11]." (PMID 30649659, 2019). "In Alzheimer’s disease, there is also a marked reduction of neurogranin levels in frontal cortex and hippocampus, the same areas of the brain where neurogranin is mostly expressed." (PMID 30649659, 2019). "Neurogranin (Ng) is a small 7.6 kDa postsynaptic protein that has been detected at elevated concentrations in cerebrospinal fluid (CSF) of patients with Alzheimer’s disease (AD), both as a full-length molecule and as fragments from its C-terminal half." (PMID 30157938, 2018). "Cerebrospinal fluid total tau, neurogranin, and neurofilament light represent different aspects of neurodegeneration in Alzheimer's disease." (PMID 27534871, 2016). "Neurogranin (Ng) expression is a biomarker for Alzheimer’s disease." (PMID 39367201, 2025).
Alzheimer disease (continued). "Our own meta-analysis confirmed elevated CSF neurogranin in Alzheimer’s disease and mild cognitive impairment, although other work suggests that neurogranin may not be entirely disease-specific." (PMID 40981206, 2025). "Neurogranin has already been established as a sensitive marker of synaptic degeneration in Alzheimer’s disease, and its altered dynamics after mTBI may represent a mechanistic link between acute synaptic injury and later-life cognitive decline." (PMID 40981206, 2025). "There is initial evidence suggesting that biomarker neurogranin (Ng) may distinguish Alzheimer’s disease (AD) from other neurodegenerative diseases." (PMID 39242539, 2024). "In the memory-clinic-based Amsterdam Dementia Cohort study, baseline CSF neurogranin levels were greater in patients with mild cognitive impairment who progressed to Alzheimer’s disease and were prognostic of progress from mild cognitive impairment to Alzheimer’s disease." (PMID 33578866, 2021). "The CSF neurogranin levels were significantly higher in patients with early symptomatic Alzheimer’s disease, and this differentiated them from controls, with diagnostic utility (0.71; 95% CI: 0.64–0.77) that was similar to other established cerebrospinal biomarkers." (PMID 33578866, 2021). "In a prospective study involving 915 patients, CSF neurogranin levels were significantly and specifically elevated in Alzheimer’s disease compared with eight other neurodegenerative diseases, including amyotrophic lateral sclerosis, Parkinson’s disease, and frontotemporal dementia." (PMID 33578866, 2021). "The levels of CSF neurogranin is elevated in Alzheimer’s disease dementia and may be specific for the disease." (PMID 33578866, 2021). "In an earlier retrospective cohort study comprised of 19 healthy controls with normal cognitive function and 331 individuals with various neurodegenerative diseases, the median CSF neurogranin level was greater in Alzheimer’s disease patients compared with the other disease groups and controls." (PMID 33578866, 2021). "This could be explained by the fact that the main brain regions affected by Alzheimer’s disease are also the regions with the highest expression of neurogranin." (PMID 30649659, 2019). "It has therefore been suggested that CSF neurogranin could be used as a specific biomarker for Alzheimer’s disease." (PMID 30649659, 2019). "In Alzheimer’s disease and mild cognitive impairment, elevated cerebrospinal fluid neurogranin levels correlate strongly with cognitive decline and progression, while blood-derived exosomal neurogranin has shown promise as a minimally invasive biomarker of early synaptic degeneration." (PMID 40981206, 2025). "Similarly, in a longitudinal study of 37 cognitively normal individuals and 65 patients with Alzheimer’s disease within the memory-clinic-based Amsterdam Dementia Cohort, baseline CSF neurogranin levels in patients with the disease were significantly higher than in cognitively normal participants." (PMID 33578866, 2021). "Neurogranin and neuronal pentraxin receptors seem to be novel, promising biomarkers that may reflect pathological changes of synaptic disturbance in patients with Alzheimer’s disease." (PMID 34640593, 2021). "Furthermore, CSF neurogranin levels projected future cognitive impairment (adjusted HR: 1.89; 95% CI: 1.29–2.78) in controls with normal cognitive function and predicted a decline in cognition in patients with symptomatic Alzheimer’s disease." (PMID 33578866, 2021). "CSF neurogranin could, perhaps, in combination with other CSF biomarkers, contributes to differentiating between HAD and other causes for neurocognitive decline, for example Alzheimer’s disease." (PMID 30649659, 2019). "Recent studies suggest that NRGN is involved in neuropsychiatric disorders, including schizophrenia, ADHD, and Alzheimer's disease." (PMID 33270377, 2021).
Alzheimer disease (continued). "Cerebrospinal fluid (CSF) measurements of neurogranin (Ng) have emerged as a promising biomarker for cognitive decline in mild cognitive impairment (MCI) and Alzheimer’s disease (AD)." (PMID 33986657, 2021). "Neurogranin (Ng) and visinin-like protein 1 (VILIP-1) are promising candidates for Alzheimer’s Disease (AD) biomarkers closely related to synaptic and neuronal degeneration." (PMID 33172069, 2020). "But also levels of synaptopodin, synaptophysin, synaptotagmins, neurogranin and GAP43 were lower in patients with Alzheimer's disease than in cognitively normal controls." (PMID 28912682, 2017). "NRGN, a human homolog of the neuron-specific rat RC3/neurogranin gene, exhibits aberrant expression in the brain and plays a role in the development of Parkinson's disease, schizophrenia and Alzheimer's disease." (PMID 38427106, 2024). "Our results suggest that neurogranin and BACE1 levels may differentiate pathomechanistic Alzheimer’s disease subgroups, putatively with different options for treatment." (PMID 36262371, 2022). "Considering the behavioral phenotypes that had been previously identified, we propose that Neurogranin KO mice are a valuable animal model that recapitulates a variety of symptoms of neuropsychiatric disorders, such as schizophrenia, ADHD, and Alzheimer's disease." (PMID 33270377, 2021). "Furthermore, neurogranin and other synaptic biomarkers such as Rab3 and SNAP25 were found to predict cognitive decline in patients with Alzheimer’s disease and dementia of Lewy bodies." (PMID 33578866, 2021). "Interestingly, a recent study including data from the Alzheimer’s Disease Neuroimaging Initiative (ADNI) showed decreasing levels of both YKL-40 and neurogranin with the progression of symptomatic late onset sporadic AD." (PMID 32568193, 2020). "CSF neurogranin levels are increased in Alzheimer’s disease, but not in other studied neurodegenerative disorders [15•]." (PMID 30649659, 2019). "CSF concentrations of neurogranin are increased in Alzheimer’s disease, but not in other neurodegenerative disorder such as Parkinson’s disease, frontotemporal dementia, Lewy body dementia, progressive supranuclear palsy, or multiple system atrophy." (PMID 30649659, 2019). "CSF concentrations of neurogranin are increased in Alzheimer’s disease, but not in other neurodegenerative disorder such as Parkinson’s disease, frontotemporal dementia, and Lewy body dementia." (PMID 30649659, 2019). "However, in a study reported nine years earlier, there were no substantial differences in CSF biomarkers such as neurogranin, t-tau, and p-tau between healthy controls with normal cognitive function and patients with Alzheimer’s disease." (PMID 33578866, 2021). "While neurogranin has no value as plasma biomarker for Alzheimer’s disease, it may be a potential blood biomarker for traumatic brain injury." (PMID 28854881, 2017).